CST2 (cystatin SA)
Diseases named in the same sentence as CST2 in open-access papers (continued):
Sharing a sentence is not in itself a finding about the gene and the disease.
tumor (14 papers, 2019 to 2025). "The results demonstrate that CST2 overexpression in pan-cancer contributes to carcinogenesis and is closely associated with the tumor immune microenvironment (TIM)." (PMID 39926600, 2024). "These insights contribute to a better understanding of the molecular mechanisms underlying CST2’s involvement in tumor initiation and progression, laying the groundwork for future research into targeted therapies and precision medicine." (PMID 39926600, 2024). "High levels of CST2 mRNA were significantly associated with poor prognosis in the histological signet ring type, tumor stage IV, residual tumor R0, radiotherapy, and target therapy in the TCGA." (PMID 37978366, 2023). "By modulating four risk genes, especially CST2, it is possible to alter the level of tumor immunity, affecting the ICPI response rate." (PMID 37346077, 2023). "CST2 gene expression was the only one found to be highly correlated with increased pathological tumor stages." (PMID 40747123, 2025). "CST2 serves as a potential tumor immune biomarker, playing a critical facilitating role in the proliferation and migration processes of STAD." (PMID 39926600, 2024). "Considering the limited number of normal samples available in TCGA, we integrated data from the GTEx and TCGA databases to analyze CST2 expression differences in 15 tumor types." (PMID 39926600, 2024). "Our research further indicates that among tumor patients receiving CAR-T cell therapy, those with CST2 overexpression are at a lower risk of mortality and demonstrate a better prognosis." (PMID 39926600, 2024). "Through comprehensive analysis and evaluation, we have discovered distinct expression patterns of CST2 across different clinical stages in several tumor types." (PMID 39926600, 2024). "Previous studies have indicated that CST2 can predict disease progression in certain non-tumor conditions." (PMID 39926600, 2024). "To determine the differential expression of CST2 between tumor and normal tissues, we conducted an analysis using the TCGA database for 33 different cancer types." (PMID 39926600, 2024). "As the results show, the mRNA expression levels of CST2 were increased as the cell status changed from normal to tumor." (PMID 37346077, 2023). "It was also found that in the metastasis samples, the expression of the CST2 gene was statistically significantly reduced by an average of 3.5-fold compared to the primary tumor samples (p = 0.002)." (PMID 36768739, 2023). "We used qRT-PCR to measure the relative mRNA expression levels of four risk genes (TIPARP, SERPINA3, MT1M, and CST2) in the normal prostate tissue cell RWPE-1 and in different tumor cell states such as LNCaP and C4-2 cell lines." (PMID 37346077, 2023). "Additionally, we accessed data from the CCLE database to investigate CST2 expression in 31 tumor cell lines." (PMID 39926600, 2024). "Collectively, these data suggest that CST2 may suppress tumor growth by inhibiting the PI3K/AKT signaling pathway in vivo." (PMID 38717526, 2024). "Furthermore, we established a xenograft model in nude mice and observed that the CST2 overexpression significantly inhibited GC tumor growth in vivo compared to the control groups." (PMID 38717526, 2024). "High CST2 mRNA levels showed significantly worse prognosis in male and female, tumor stage III and IV, Lauren classification as intestinal and diffuse, poorly differentiated tumor, surgery alone as treatment, and positive and negative HER2 status in the KM plotter online database." (PMID 37978366, 2023). "Further investigation is necessary to establish whether CST2 can serve as a novel target for cancer diagnosis, treatment, and prognosis across different cancer types, as well as its potential value in predicting the efficacy of anti-tumor immune responses." (PMID 39926600, 2024). "Nomograms were drawn based on CST2 and CST4 expression levels, age, tumor stage, cancer status, residual tumor, and targeted therapy." (PMID 37978366, 2023).
tumor (continued). "Moreover, after searching the immunohistochemistry (IHC) staining results, the pictures for CST2 and SERPINA3 in normal and tumor tissues in the HPA database were similar." (PMID 37346077, 2023). "In addition, we analyzed the gene expression profile of GSE85841 that included eight LUAD samples and adjacent non-tumor samples with adjusted P < 0.05 and logFC≥1.5, and researched the top five most significantly upregulated genes: SFRP5, CST2, SPP1, GCNT3, and NHLRC1." (PMID 35399076, 2022). "CST2 expression differed only between LUAD and non-tumor tissues, and NHLRC1 expression differed between LUSC and non-tumor tissues." (PMID 35399076, 2022).
cancer (8 papers, 2021 to 2025). A tumor composed of atypical neoplastic, often pleomorphic cells that invade other tissues. "As members of the type 2 cystatin (CST) superfamily, CST1(Cystatin SN) and CST2(Cystatin SA) have been reported to be capable of inhibiting the proteolytic activities of cysteine proteases and is implicated in progression of several human cancers." (PMID 40761581, 2025). "Hence, further exploration of the mechanisms underlying CST2’s involvement in tumors holds significant importance in providing new directions and strategies for clinical cancer treatment." (PMID 39926600, 2024). "Therefore, CST2 holds promise as a diagnostic marker for detecting mutations and epigenetic alterations across various types of cancer." (PMID 39926600, 2024). "The correlation heatmap reveals that CST2 is closely associated with various immune cells in pan-cancer, including cancer-associated fibroblasts (CAF), endothelial cells, hematopoietic stem cells, regulatory T cells (Tregs), B cells, macrophages, monocytes, myeloid dendritic cells, and CD8+ T cells." (PMID 39926600, 2024). "Therefore, dysregulation of CST2 is implicated in human cancer." (PMID 39926600, 2024). "In summary, CST2 represents a promising therapeutic target in cancer treatment and serves as a potential biomarker for predicting immunotherapy efficacy and prognosis." (PMID 39926600, 2024). "Previous studies have shown that CST2 expression can potentially influence the efficacy of chemotherapy in cancer patients." (PMID 38717526, 2024). "To further explore the impact of CST2 on cancer cell proliferation, we conducted colony formation assays." (PMID 39926600, 2024). "The single-cell analysis results reveal distinct expression patterns of CST2 across various cancer types." (PMID 39926600, 2024). "We utilized gene set enrichment analysis (GSEA) analysis to explore the biological functions of CST2 across different cancer types." (PMID 39926600, 2024). "The current study also showed that CST2 mRNA expression was upregulated in multiple types of cancers." (PMID 34335931, 2021). "This study comprehensively analyzes the differential expression of CST2 in pan-cancer." (PMID 39926600, 2024). "Nevertheless, there remains a need for a comprehensive understanding of CST2’s role in pan-cancer." (PMID 39926600, 2024). "Additionally, the levels of apoptosis were significantly increased in both cell lines following CST2 knockdown, further supporting the influence of CST2 on cancer cell survival." (PMID 39926600, 2024). "In pan-cancer analysis, a significant correlation is observed between CST2 and methylation." (PMID 39926600, 2024). "We have observed a significant correlation between CST2 and methylation in pan-cancer." (PMID 39926600, 2024). "However, more research is still needed to confirm the overexpression of CST2 and its oncogenic role in cancer." (PMID 39926600, 2024). "Thus, CST2 can serve as a predictive biomarker for immunotherapy efficacy in these specific cancers." (PMID 39926600, 2024). "Additionally, overexpression of CST2 at both mRNA and protein levels is correlated with poor prognosis in late-stage cancer across multiple types, emphasizing its significance in cancer progression." (PMID 39926600, 2024). "Emerging research indicates that CST2 is often dysregulated across various cancers." (PMID 38717526, 2024). "Taken together, these findings are consistent with the hypothesis that SELP and CST2 may act as cancer progression-promoting genes in various tumors." (PMID 37061682, 2023). "This suggests that CST2 upregulation might be a common occurrence and play an essential role during the development of various types of cancers." (PMID 34335931, 2021). "In our study, we discovered that CST2 is closely associated with multiple immune cells, including CAFs, endothelial cells, hematopoietic stem cells, regulatory T cells (Tregs), B cells, macrophages, monocytes, myeloid dendritic cells, and CD8+ T cells, in pan-cancer." (PMID 39926600, 2024).
cancer (continued). "Therefore, CST2 represents an attractive therapeutic target in cancer treatment." (PMID 39926600, 2024). "Cystatin SA (CST2) and Cystatin S (CST4) are known to be present in seminal fluid, have anti-viral properties and elevated levels have been reported for many cancer types including PCa39–41." (PMID 41258098, 2025). "Cystatin 2 (CST2) is a cysteine protease inhibitor, and recent research suggests its potential involvement in cancer development." (PMID 39926600, 2024). "Further investigations demonstrated a significant correlation between CST2 expression and PFI in several cancer categories, including STAD, SKCM, READ, PAAD, LGG, KIRC, GBM, and COAD." (PMID 39926600, 2024).
CST2 also shares sentences with these, for which no sentence is quoted: nasal polyp (2 papers); allergic rhinitis (1); Anxiety (1); asthma (1); cholangiocarcinoma (1); colon cancer (1); endometrial cancer (1); esophageal carcinoma (1); esophageal squamous cell carcinoma (1); infection (1); lung adenocarcinoma (1); lung squamous cell carcinoma (1); non-small cell lung carcinoma (1); periodontal disease (1); prostate adenocarcinoma (1); prostatitis (1); staphylococcus aureus infection (1); thyroid cancer (1); Urothelial bladder cancer (1); uterine corpus endometrial carcinoma (1).